CGAS (cyclic GMP-AMP synthase)
Diseases named in the same sentence as CGAS in open-access papers (continued):
Sharing a sentence is not in itself a finding about the gene and the disease.
HCMV infection (20 papers, 2016 to 2025). "Recent results obtained by our group have demonstrated that the pyrin association domain (PAD) of pp65 binds cGAS, thereby inhibiting its enzymatic activity upon HCMV infection." (PMID 32351486, 2020). "The degree of cGAS-dependent cGAMP formation correlated with the susceptibility of different monocyte-derived cell subset to HCMV infection." (PMID 27058035, 2016). "Thus, it is very unlikely that single nucleotide polymorphisms that influence the functionality of components of the cGAS/STING axis affect the susceptibility of healthy individuals to HCMV infection." (PMID 31249303, 2019). "UL31 fails to inhibit cGAMP induction of Type I ISGs but is capable of inhibiting the interferon-associated gene transcription stimulated by both HCMV infection and dsDNA, signifying that this key interaction with cGAS is critical for modulating downstream immune signaling." (PMID 30134546, 2018). "Furthermore, impaired IFR3 phosphorylation and IFN-β induction in cGAS or STING deficient monocytic THP-1 cells demonstrated that the cGAS/STING axis was required for efficient IFN-I expression upon HCMV infection." (PMID 27058035, 2016). "This led us to hypothesize that the susceptibility to CMV infection was one prerequisite for the engagement of the cytoplasmic cGAS/STING axis in CMV sensing." (PMID 27058035, 2016). "Therefore, we hypothesize that the susceptibility to HCMV infection determines the accessibility of the viral genome to cGAS, thus directly affecting the magnitude of cGAMP responses." (PMID 27058035, 2016). "Overall, our work identifies an additional viral protein that is regulated by protein-S-nitrosylation in the cGAS/STING pathway in HCMV infection." (PMID 40243337, 2025). "To further understand the impact of protein-S-nitrosylation on pp65 in HCMV infection, we determined if DM-pp65 demonstrates altered binding to cGAS compared to WT pp65 and if pp65 is protein-S-nitrosylated in the absence of infection." (PMID 40243337, 2025). "We wanted to determine if cGAS is degraded in DM-pp65 HCMV infection and if so, what mechanisms lead to the degradation of cGAS compared to WT HCMV infection." (PMID 40243337, 2025). "Here, we show that the cGAS-STING-TBK1 pathway promotes VPA-responsive IE gene expression during HCMV infection of incompletely differentiated myeloid cells in the absence of UL138." (PMID 38932169, 2024). "Treatment with Ru.521 did not affect cell viability, but it inhibited the induction of IFNB1 transcripts following infection with AD169, confirming that cGAS activity is required for the IFN-I response to HCMV infection in THP1 cells." (PMID 38932169, 2024). "IFN1 production in HCMV infection is triggered by cytoplasmic sensors such as cyclic GMP-AMP synthase (cGAS) and retinoic acid inducible gene I (RIG-I)-like receptor (RLR), which specifically sense viral DNA or RNA and induce antiviral signaling." (PMID 36939338, 2023). "The cGAS/STING/TBK1 pathway has been shown to mediate an IFN response to HCMV infection in fibroblasts (10, –, 14), endothelial cells, macrophages, and dendritic cells." (PMID 34903048, 2021). "STING is a key regulator in innate immune signaling downstream of cGAS recognition of incoming viral DNA including the response to HCMV infection." (PMID 34411201, 2021). "cGAS/STING pathway activation contributes to increased IL-1β secretion after HCMV infection through the upregulation of AIM2." (PMID 34372578, 2021). "Endogenous co-immunoprecipitation experiments indicated that UL42 was associated with both cGAS and MITA following HCMV infection." (PMID 31107917, 2019). "Multiple reports have implicated ISGylation as an anti-viral defense mechanism that is triggered early during HCMV infection via cGAS-STING viral DNA sensing and restricts HCMV replication." (PMID 30134546, 2018). "Presumably monocyte-derived cells are dependent on HCMV infection in order to activate cGAS and thus to mount IFN-α responses." (PMID 30403913, 2018).
HCMV infection (continued). "This suggests that the soluble antiviral factor that reduced viral spread in the epithelial cells also reduced the vulnerability of macrophages to HCMV infection and thus impaired the activation of cGAS-mediated IFN-I responses by the macrophages." (PMID 30403913, 2018). "The cGAS-STING pathway is critical for activating the type I IFN pathway upon HCMV infection in primary human umbilical vein endothelial cells (HUVEC) and monocytic leukemia cell line THP-1." (PMID 29018427, 2017). "DNA sensors such as DNA-dependent activator of IFN-regulatory factors (DAI), IFI16 or cGAS were reported to detect HCMV infection to induce type I IFN activation." (PMID 29018427, 2017). "For instance, endothelial cells were identified as the master regulators of cytokine storm during infection with influenza virus; and human cytomegalovirus infection led to a robust type I IFN response dependent on the cGAS-STING signaling in primary human endothelial cells." (PMID 30620752, 2019). "Importantly, HCMV infection of THP-1 cells is known to trigger IRF3-mediated IFN responses in a cGAS/STING-dependent manner." (PMID 30755509, 2019). "Interestingly, the magnitude of cGAS activation, as determined by intracellular concentrations of the second messenger cGAMP, correlated with the extent of HCMV infection of the respective cell subset." (PMID 30403913, 2018). "The cGAS-STING pathway may play an important role in the type I IFN pathway upon HCMV infection because KD of either cGAS or STING strongly abolishes activation of TBK1 and IRF3." (PMID 29018427, 2017). "HCMV infection further induced cGAS, whereas STING expression was only moderately affected." (PMID 27058035, 2016). "Interestingly, stimulation with recombinant IFN-α2b and HCMV increased cGAS mRNA expression to a similar extent, although upon HCMV infection IFN-I production of single myeloid cell subsets differed significantly." (PMID 27058035, 2016). "Taken together, these data suggest that the role in promoting IFNB1 and VPA-responsive IE gene expression downstream of cGAS/STING during HCMV infection is specific to TBK1 and that IKKε may instead restrict viral gene expression during HCMV infection of incompletely differentiated myeloid cells." (PMID 38932169, 2024). "We conclude that cGAS and STING promote both IFN-I and VPA-responsive viral IE gene expression during HCMV infection of incompletely differentiated myeloid cells." (PMID 38932169, 2024). "Taken together, these data suggest that the cGAS/STING activity promotes VPA-responsive IFNB1 and viral IE gene expression during HCMV infection of incompletely differentiated myeloid cells." (PMID 38932169, 2024). "We next wanted to exclude that diminished innate immune responses after HCMV infection are due to the activity of ATRX as an antiviral restriction factor and additionally prove a direct effect of ATRX on the cGAS-STING DNA sensing pathway." (PMID 35939517, 2022). "We conclude that UL138 inhibits the cGAS/STING/TBK1 innate immune response in 293T cells, in fibroblasts (in which HCMV infection is lytic), and in THP-1 cells (in which HCMV infection is latent)." (PMID 34903048, 2021). "We used a return-of-function approach as a first examination of the effects of UL138 on the cGAS/STING/TBK1 pathway and IFN-β mRNA accumulation during HCMV infection." (PMID 34903048, 2021). "Our work has identified the first inhibitor of cGAS/STING/TBK1 that is expressed and functions during latent HCMV infections within incompletely differentiated myeloid cells." (PMID 34903048, 2021). "For instance, HCMV infection of mDCs in vitro triggers IFN and IL-12 release in a cGAS-dependent manner." (PMID 32351486, 2020). "cGAS activity plays a major role in the STING/tank-binding kinase (TBK-1)/IRF3 pathway, activated by herpes simplex virus type 1 (HSV-1) and HCMV infection." (PMID 32351486, 2020).
HCMV infection (continued). "HCMV-infected monocyte-derived cells generated abundant cGAMP, and knockdown or knockout of cGAS in THP-1 monocytes and primary monocyte-derived cells attenuated IFN-I response, supporting the conclusion that cGAS senses HCMV infection." (PMID 31234396, 2019). "Cellular and biochemical experiments indicated that UL42 interacted with cGAS and MITA following HCMV infection." (PMID 31107917, 2019). "While IFI16 induces cytokines, only cGAS activates STING/TBK-1/IRF3 and apoptotic responses upon HSV-1 and HCMV infections." (PMID 27935834, 2016). "CRISPR/Cas9- or siRNA-mediated cGAS ablation in monocytic THP-1 cells and primary monocyte-derived cells, respectively, impeded induction of IFN-I responses following HCMV infection." (PMID 27058035, 2016). "This was in line with previous reports that cGAS is not degraded during HCMV infections, where wild-type pp65 is expressed." (PMID 40243337, 2025). "In addition to its known role in repressing the MIEP, UL138 inhibits the cGAS-STING-TBK1 pathway and limits the accumulation of IFNB transcripts during both lytic and latent HCMV infection." (PMID 38932169, 2024). "As the cGAS-STING DNA sensing pathway is crucial for the initial cellular response to DNA viruses, we wanted to further characterize the role of ATRX in the DNA sensing pathway during HCMV infection." (PMID 35939517, 2022). "Because cGAS and STING are key sensors of HCMV in primary human monocyte-derived DCs and macrophages, our data may explain the mechanism through which HCMV infection activates p65 transcription." (PMID 33072119, 2020). "Interestingly, no degradation of cGAS was observed at any of the time points of HCMV infection in our study." (PMID 40243337, 2025). "Although pDC expressed particularly high levels of cGAS, and the cGAS/STING axis was functional down-stream of STING, as indicated by IFN-I induction upon synthetic cGAMP treatment, pDC were not susceptible to HCMV infection and mounted IFN-I responses in a TLR9-dependent manner." (PMID 27058035, 2016). "Although IFI16 knockdown (KD) enhances HCMV replication, a recent study indicates that cGAS, but not IFI16, is required for the STING signaling pathway in human fibroblast upon HCMV infection." (PMID 29018427, 2017).
non-small cell lung carcinoma (20 papers, 2020 to 2025). A group of at least three distinct histological types of lung cancer, including non-small cell squamous cell carcinoma, adenocarcinoma, and large cell carcinoma. "cGAS mRNA expression was correlated with CIN in EGFR-mutated non-small-cell lung cancer." (PMID 40136696, 2025). "The reconstructed mathematical model presented here offers a system-level perspective of the cGAS–STING–FOXO regulatory axis in mediating autophagy within non-small cell lung cancer (NSCLC) cells." (PMID 41378291, 2025). "And other studies have shown that YAP1 and cGAS-STING are positively correlated in non-small cell lung cancer." (PMID 40918140, 2025). "Gene and protein expression of the cGAS-STING signaling pathway was characterized in a series of non-small cell lung cancer (NSCLC) cell lines." (PMID 40012911, 2024). "cGAS-STING signaling pathway was also associated with the suppression of YAP1 in endothelial cells and non-small cell lung cancer." (PMID 37406004, 2023). "For example, lncRNA PCAT1 reportedly suppresses the radioimmune response by regulating cGAS/STING signaling in non-small cell lung cancer." (PMID 37596700, 2023). "While cGAS is often regulated at the level of protein stability, HSV infection of neonates also leads to increased levels of cGAS transcription and similar increases are seen in vivo in tumors such as non-small-cell lung cancers." (PMID 35877778, 2022). "For example, loss of cGAS-STING signalling in hepatocellular carcinoma resulted in enhanced tumorigenicity and decreased CTL infiltration in non-small-cell lung carcinoma (NSCLC)." (PMID 33081170, 2020). "This study aims to investigate the association between SWI/SNF gene ARID1B mutation and ICI response in non-small cell lung cancer (NSCLC) patients, to explore the functional consequences of ARID1B mutation on DNA damage response, immune microenvironment, and cGAS-STING pathway activation." (PMID 38577613, 2024). "The experimental results showed that GF alone or in combination with radiotherapy could induce the production of the micronucleus (MN) in vitro and in vivo and activate the cyclic GMP-AMP synthase (cGAS) in non-small-cell lung cancer cells." (PMID 39314753, 2024). "In patients with defective Excision Repair Cross-Complementation Group 1 (ERCC1), a particular homologous repair deficiency, with non-small cell lung cancer (NSCLC), PARPi therapy created cytoplasmic chromatin fragments that triggered cGAS/STING to produce type I IFNs and CCL5." (PMID 38542143, 2024). "Moreover, cGAS knockdown inhibits tumor growth in in vivo mouse model using non-small cell lung carcinoma, indicating that cGAS promotes tumorigenesis." (PMID 39424777, 2024). "Interestingly, cGAS knockdown in non-small cell lung carcinoma suppresses tumor growth in a xenograft mouse model, indicating that cGAS promotes tumorigenesis." (PMID 39424777, 2024). "Olaparib and rucaparib treatment modulate the immune response through the cGAS/STING pathway in ERCC1-defective, non-small cell lung cancer (NSCLC) and BRCA1-defective TNBC cells." (PMID 34885119, 2021).
diabetic cardiomyopathy (19 papers, 2021 to 2026). Diabetic cardiomyopathy is a disorder of the heart muscle in people with diabetes. "Around the same time, another study highlighted that oxidative mitochondrial damage caused by lipid toxicity in diabetic cardiomyopathy led to the cytosolic release of mtDNA, subsequently activating the cGAS/STING pathway." (PMID 40497954, 2025). "Mitochondrial dysfunction is a hallmark of diabetic cardiomyopathy, and recent evidence suggests that activation of the cGAS-STING signaling pathway may contribute to metabolic inflammation in the atria." (PMID 41356195, 2026). "In diabetic cardiomyopathy, fatty acid-driven mtDNA release provokes cardiomyocyte pyroptosis via the cGAS–STING pathway." (PMID 41009042, 2025). "In diabetic cardiomyopathy, free fatty acid–induced mtDNA release into the cytosol activates cGAS–STING, triggering pyroptosis and inflammatory responses that drive cardiac hypertrophy." (PMID 41009042, 2025). "Building on these mechanistic insights, several studies have proposed therapeutic strategies targeting the cGAS/STING pathway in diabetic cardiomyopathy." (PMID 40497954, 2025). "Inhibition or genetic deletion of cGAS or STING has been demonstrated to attenuate the development of diabetic cardiomyopathy and improve cardiac function in these models." (PMID 39853716, 2025). "Collectively, these findings highlight the central roles of mitochondrial dysfunction and cGAS/STING activation in the pathogenesis of diabetic cardiomyopathy." (PMID 40497954, 2025). "Mechanistic studies revealed that it was associated with the activation of the cGAS-STING-induced cardiomyocyte focal death, worsening the progression of diabetic cardiomyopathy and leading to myocardial hypertrophy." (PMID 38720328, 2024). "Mitochondrial metabolic stress has been reported to contribute to diabetic cardiomyopathy by mtDNA-mediated activation of the cGAS–STING pathway." (PMID 35915611, 2022). "Recently, STING has been reported to be involved in islet damage, cholesterol metabolism and liver inflammation, thus it can be seen that cGAS-STING signaling is closely related to diabetic cardiomyopathy." (PMID 36072862, 2022). "Additionally, Metrnl improves diabetic cardiomyopathy and reduces heart cell damage by inhibiting cGAS/STING signaling through autophagy, but also attenuates adriamycin-induced cardiotoxicity via activation of the cAMP/PKA/SIRT1 pathway." (PMID 40082768, 2025). "Similarly, studies have shown that cGAS-STING pathway expression is decreased in diabetic cardiomyopathy mice to promote the progression of type 1 diabetes." (PMID 37762143, 2023). "Activation of the cGAS/STING pathway has been shown to promote cardiac fibrosis, hypertrophy and contractile dysfunction in animal models of diabetic cardiomyopathy." (PMID 39853716, 2025). "Notably, activation of TBK1 and its upstream cyclic GMP-AMP synthase–stimulator of interferon gene (cGAS-STING) pathway has been confirmed in diabetic cardiomyopathy and pharmacologically inhibited STING could effectively reduce its inflammation-related damage and pyroptosis." (PMID 39030571, 2024). "The activation of the cGAS-STING inflammatory pathway is also induced by cytoplasmic mtDNA, thus accelerating the development of diabetic cardiomyopathy." (PMID 38312740, 2024). "In 2023, another group showed that irisin—a myokine—rescued cardiac dysfunction in diabetic cardiomyopathy by activating mitochondrial ubiquitin ligase MITOL (also known as MARCH5) and suppressing NLRP3 inflammasome activity through the inhibition of the cGAS/STING pathway." (PMID 40497954, 2025).
heart failure (19 papers, 2020 to 2025). Inability of the heart to pump blood at an adequate rate to meet tissue metabolic requirements. "Understanding the intricate mechanisms underlying the cGAS-STINGpathway in cardiac remodeling may pave the way for novel therapeutic strategiestargeting this pathway to alleviate heart failure progression." (PMID 39076568, 2024). "Recent studies have shown that the cGAS-STING pathway activated is closely associated with CVDs, such as AS, aortic aneurysms and dissections (AAD), and heart failure (HF)." (PMID 38720328, 2024). "Blocking cGAS-STING signaling in pressure overload-induced heart failure leads to lower levels of chemokines, inflammatory cytokines, and inflammatory cell infiltration in cardiac tissues, as well as better cardiac function." (PMID 36964634, 2023). "cGAS-STING pathway activation in human heart failure samples was confirmed by the dynamic changes in cGAS and CXCL10, which were consistent with those observed in mice." (PMID 37163421, 2023). "Furthermore, in heart failure, cGAS-STING signaling gradually escalates, further fostering pathological cardiac remodeling and left ventricular dysfunction 30-32." (PMID 38818463, 2024). "In addition, high expression levels of genes related to the cGAS–STING signaling pathway have been associated with cardiac insufficiency (irrespective of the causative factors), and when the cGAS–STING signaling pathway is inhibited, cardiac function is significantly restored." (PMID 38525112, 2024). "The cGAS-STING pathway has been recognized as a significant contributor tocardiac remodeling and the development of heart failure, a complex andprogressive cardiovascular disorder." (PMID 39076568, 2024). "Evidence has been accumulating that cGAS/STING might play an important role in pathologies beyond classical immune diseases, as in, for example, cardiac failure." (PMID 35406723, 2022). "DNA, as an important DAMPs, could be sensed by cGAS and activates cGAS-STING-IRF7 pathway during MI of mouse and human heart failure." (PMID 35186921, 2022). "Finally, in human patients with atrial fibrillation who subsequently develop heart failure, serum cGAMP concentration, a product of CGAS activity, was higher than in those who do not develop heart failure." (PMID 40180542, 2025).